IGHV2-70 (immunoglobulin heavy variable 2-70)
Description:
V region of the variable domain of immunoglobulin heavy chains that participates in the antigen recognition. Immunoglobulins, also known as antibodies, are membrane-bound or secreted glycoproteins produced by B lymphocytes. In the recognition phase of humoral immunity, the membrane-bound immunoglobulins serve as receptors which, upon binding of a specific antigen, trigger the clonal expansion and differentiation of B lymphocytes into immunoglobulins-secreting plasma cells. Secreted immunoglobulins mediate the effector phase of humoral immunity, which results in the elimination of bound antigens. The antigen binding site is formed by the variable domain of one heavy chain, together with that of its associated light chain. Thus, each immunoglobulin has two antigen binding sites with remarkable affinity for a particular antigen. The variable domains are assembled by a process called V-(D)-J rearrangement and can then be subjected to somatic hypermutations which, after exposure to antigen and selection, allow affinity maturation for a particular antigen.
Synonyms: IGHV270; VH
Tractability: Antibody: its Gene Ontology location is reachable by antibodies, with high confidence; UniProt places it where antibodies can reach, with medium confidence; UniProt predicts a signal peptide or a membrane-spanning region.
Gene: Immunoglobulin variable (V) gene on chromosome 14 (106,770,577 to 106,771,020, reverse strand). Ensembl gene ENSG00000274576.
Subcellular location: Secreted; Cell membrane
Pathways (Reactome):
Immune System: Antigen activates B Cell Receptor (BCR) leading to generation of second messengers; CD22 mediated BCR regulation; Classical antibody-mediated complement activation; FCERI mediated Ca+2 mobilization; FCERI mediated MAPK activation; FCERI mediated NF-kB activation; FCGR activation; Fc epsilon receptor (FCERI) signaling; Immunoregulatory interactions between a Lymphoid and a non-Lymphoid cell; Initial triggering of complement; Regulation of Complement cascade; Regulation of actin dynamics for phagocytic cup formation; Role of LAT2/NTAL/LAB on calcium mobilization; Role of phospholipids in phagocytosis
Disease: FCGR3A-mediated IL10 synthesis; FCGR3A-mediated phagocytosis; Potential therapeutics for SARS
Hemostasis: Cell surface interactions at the vascular wall
Vesicle-mediated transport: Scavenging of heme from plasma
Gene Ontology:
Molecular function: antigen binding
Biological process: immune response; immunoglobulin mediated immune response
Cellular component: extracellular region; plasma membrane
Homologues: Orthologues: mouse Ighv8-12 (71% identical), mouse Ighv8-8 (71% identical), mouse Ighv8-6 (71% identical), mouse Ighv8-5 (69% identical), mouse Ighv8-9 (69% identical), mouse Ighv8-11 (66% identical), rat AABR07065813.1 (66% identical), mouse Ighv8-4 (62% identical), mouse Ighv8-13 (61% identical), mouse Ighv8-2 (61% identical), rat Igh-6-ps1 (52% identical). Paralogues in human: IGHV2-70D (97% identical), IGHV2-5 (87% identical), IGHV2-26 (84% identical), IGHV2OR16-5 (84% identical), IGHV4-39 (54% identical), IGHV4-59 (54% identical), IGHV4-61 (54% identical), IGHV4-28 (53% identical), IGHV4-31 (53% identical), IGHV4-4 (51% identical), IGHV4OR15-8 (50% identical), IGHV4-34 (50% identical), and 65 more.